CCDC18 (coiled-coil domain containing 18)
Description:
May promote pre-adipocyte differentiation.
Synonyms: NY-SAR-41
Tractability: PROTAC: ubiquitination databases record sites on it.
Gene: Protein-coding gene on chromosome 1 (93,179,895 to 93,279,048, forward strand). Ensembl gene ENSG00000122483.
Subcellular location: Cytoplasm, cytoskeleton, microtubule organizing center, centrosome, centriolar satellite
Subcellular location (Human Protein Atlas): Nucleoplasm; Cytosol
Gene Ontology:
Biological process: positive regulation of adipose tissue development
Cellular component: centriolar satellite
Genetic constraint (gnomAD): Loss-of-function variants: 54 observed, 75.18 expected, observed/expected ratio (o/e) 0.72, 90% interval 0.58 to 0.9. The upper end of that interval is the gene's LOEUF score, 0.9, which puts it in group 3 of 6, group 1 being the genes least tolerant of losing a copy. Missense variants: 757 observed, 840.03 expected, observed/expected ratio (o/e) 0.9, 90% interval 0.85 to 0.96. Synonymous variants: 266 observed, 289.22 expected, observed/expected ratio (o/e) 0.92, 90% interval 0.83 to 1.02.
Homologues: Orthologues: chimpanzee CCDC18 (99% identical), macaque CCDC18 (98% identical), dog CCDC18 (90% identical), pig CCDC18 (90% identical), rabbit CCDC18 (90% identical), guinea pig CCDC18 (85% identical), mouse Ccdc18 (84% identical), rat Ccdc18 (84% identical), tropical clawed frog ccdc18 (39% identical), zebrafish ccdc18 (30% identical), zebrafish si:ch73-389b16.1 (3% identical). Paralogues in human: CEP63 (8% identical), DEUP1 (7% identical).
Diseases named in the same sentence as CCDC18 in open-access papers:
CCDC18 is named in the same sentence as 9 diseases in open-access papers, as found by Europe PMC text mining. Sharing a sentence is not in itself a finding about the gene and the disease. The quoted sentences say what the papers report.
colorectal cancer (1 paper, 2022). A primary or metastatic malignant neoplasm that affects the colon or rectum. "With the application of exome sequencing, CCDC18 was identified as a candidate susceptibility gene for common familial colorectal cancer." (PMID 36496360, 2022).
lung adenocarcinoma (1 paper, 2019). A carcinoma that arises from the lung and is characterized by the presence of malignant glandular epithelial cells. "They reported that SRGN, TPM3, THBS1, HUWE1, and CCDC18 were enriched in lung adenocarcinoma extracellular vesicles." (PMID 30646616, 2019).
Obesity (1 paper, 2024). Accumulation of substantial excess body fat. "Among these genes, AHI1, AKAP9, ANKRD12, CCDC18, IFT74, NEXN, etc., have been shown to play an important role in adipose deposition or obesity." (PMID 38474122, 2024).
cancer (3 papers, 2013 to 2018). A tumor composed of atypical neoplastic, often pleomorphic cells that invade other tissues. "The molecular mechanism of the gene CCDC18 in cancer requires further research to discover its driving genetic role in LUAD patients." (PMID 30498398, 2018).
CCDC18 also shares sentences with these, for which no sentence is quoted: fatty liver (1 paper); glioma (1); leukemia (1); liver disease (1); pancreatic cancer (1).